AGR2 (anterior gradient 2, protein disulphide isomerase family member)
Diseases named in the same sentence as AGR2 in open-access papers (continued):
Sharing a sentence is not in itself a finding about the gene and the disease.
tumor (continued). "In the context of TME, it is necessary to better understand the underlying molecular mechanisms of tumour cell secretion and as such AGR2 has been identified as a key player in such functions." (PMID 31710263, 2019). "The first clues were derived from genomic analysis of tumor versus normal tissue which demonstrated increased expression of AGR2 mRNA is linked to many different cancer types, including breast, prostate and pancreatic cancer." (PMID 29937991, 2018). "We aimed to validate the association of tumor AGR2 mRNA expression with disease-specific survival (DSS) and identify differentially expressed signaling pathways between high and low AGR2 expression tumor groups." (PMID 29796176, 2018). "This cancer specificity would make AGR2 an attractive tumor-associated antigen for therapeutic targeting." (PMID 26894971, 2016). "The expression of AGR2 was also associated with tumor size and with increased AGR2 expression in T2 (n = 37) and T3 category (n = 13) compared with the T1 category (n = 9)." (PMID 25871396, 2015). "In contrast, several PTC samples (PTC classical variant: 23 out of 28 samples; PTC follicular variant: 5 out of 11 samples) were strongly positive for AGR2 expression, and positivity was confined to tumor cells (inset 2)." (PMID 24976026, 2014). "Anterior gradient 2 (AGR2) has been implicated in tumor-associated phenotypes such as cell viability, invasion and metastasis in various human cancers." (PMID 25367337, 2014). "Our findings implicate that AGR2 expression augments tumor-associated phenotypes by increasing proliferative and invasive capacities of the ampulla of Vater cancer cells." (PMID 25367337, 2014). "Its high expression is associated with tumor metastasis and poor prognosis, while silencing AGR2 inhibits cell growth and cell cycle progression, and induces cell death." (PMID 24717913, 2014). "More biological studies in these cancer cell lines have indicated a significant role for AGR2 in tumor-associated pathways, including tumor growth, cellular transformation, cell migration, limb regeneration, and metastasis." (PMID 23029506, 2012). "Within the ERα-positive group of patients, the association between immunocytochemical staining for AGR2 (at the 1% cut-off level) and patient survival was assessed further within subgroups defined by the other tumour variables." (PMID 16598187, 2006). "Staining for AGR2 was also significantly associated with low tumour grade (Fisher's Exact test, P<0.0001)." (PMID 16598187, 2006). "As expected, the majority of the ERα-positive tumours were grades 1 or 2 (n=177) and within this subgroup staining for AGR2 was also associated with poorer patient survival (log rank test, P=0.009; Wilcoxon test χ2=5.8, 1 d.f.; P=0.02)." (PMID 16598187, 2006). "Mechanistically, AGR2 is associated with cancer cell survival, proliferation, and migration, with data provided by RNA interference and in vivo silencing data demonstrating reduced tumor growth and increased chemosensitivity." (PMID 41200187, 2025).
tumor (continued). "Consequently, the expression of anterior gradient 2 (AGR2), a protein associated with tumor growth and metastasis, is upregulated, further enhancing cancer aggressiveness." (PMID 38341509, 2024). "Consequently, the expression of AGR2, a protein associated with tumor growth and metastasis, is upregulated, which further enhances cancer aggressiveness." (PMID 38341509, 2024). "AGR2 overexpression is closely linked to tumor prognosis, often indicating a poor prognosis." (PMID 39062458, 2024). "Overall, restrained AGR2 may associate with the loss of tumor epithelial properties, resulting in diminished tumor cell adhesion and performing a malignant phenotype with metastasis-associated traits." (PMID 37121942, 2023). "As yet, the functions by which AGR2 promotes carcinogenesis growth are poorly understood in EOC, but it has been demonstrated, in diverse adenocarcinomas, roles of AGR2 in different tumour-associated processes such as proliferation, migration, invasion and metastasis." (PMID 34452625, 2021). "AGR2 is a protein disulphide isomerase regulating protein folding in endoplasmic reticulum which is important for survival of tumor cells, as many tumor cells produce abundant proteins which would cause proteotoxic stress to cells in case of insufficient or inappropriate protein-folding." (PMID 30665445, 2019). "Similarly, AGR2 protein was significantly elevated in both serum and tissue samples of pharyngeal nasal cancers, and the increased levels were associated with tumor node metastasis and relapse along with the low survival rates of patients." (PMID 31247903, 2019). "Pathway analyses suggested that increased AGR2 was associated with endoplasmic reticular homeostasis, possibly allowing tumor cells to overcome hypoxic stress and meet the increased protein demand of tumorigenesis, thereby preventing unfolded protein response-mediated apoptosis." (PMID 29796176, 2018). "Furthermore, a previous study has shown that anterior gradient homolog 2 (AGR2) is associated with increased tumor metastasis." (PMID 25825984, 2015). "To determine if modulations of AGR-2 levels during tumor growth and metastasis is associated with altered integrin levels and function, we determined the expression of a panel of integrins (α4, α5, αV, β1, β3, β4, β5 integrins) in PC3AGR−2sh and PC3Control cells by Western blotting." (PMID 24587138, 2014). "However, SNU-478:KD cells tended to be less invasive than SNU-478:VEC cells, suggesting a weak association of AGR2 expression with tumor invasiveness." (PMID 25367337, 2014). "The mechanism underlying the AGR2-associated tumor promotion has been being investigated recently." (PMID 25367337, 2014). "Subsequent studies have explored the ER-positive tumor population and shown that AGR2 is inversely associated with overall and relapse-free survival, prompting us to ask whether AGR2 plays a critical role in more-invasive ER-positive tumors." (PMID 20525379, 2010). "Notably, the expression of STOX2 and AGR2 had been previously linked to tumor progression." (PMID 36232621, 2022). "Therefore, collectively, our data suggest, the upregulation of AGR2 is an early event in endometrial carcinogenesis and is associated with well differentiated tumours but may also contribute to the tumour progression and metastasis in a subset of those ECs." (PMID 30140383, 2018). "Although AGR2 expression was associated with longer time to recurrence in higher stage cancers, AGR2 did not significantly associate with any other clinicopathological variables in this subgroup, such as Gleason score, lymph node status, tumor margins, or PSA levels." (PMID 21144054, 2010).
tumor (continued). "For the three PMP tumors (P8629, P8639 and P8605), MUC2 and AGR2 had intense staining among the epithelial tumor cells." (PMID 40018643, 2025). "In summary, extensive research on KAI1, MACC1, and AGR2 has illustrated their involvement in tumor invasion and metastasis." (PMID 41239615, 2025). "Proteins that either promote or inhibit AGR2 dimerization have been identified, indicating a complicated, regulated role for AGR2 in carrying out functions in the ER, cell signaling, and the tumor microenvironment." (PMID 40867591, 2025). "We also excluded five markers that showed expression in both tumor subtypes (AGR2, SNAI2, KRT6A, MET, SLC16A3)." (PMID 39935174, 2025). "The cytosolic relocalization of the PDI-like proteins such as AGR2 confers a survival advantage to tumor cells frequently exposed to chronic stress by inhibiting proapoptotic pathways." (PMID 40839310, 2025). "Pro-tumor TANs display altered metabolic activity and secrete factors that promote angiogenesis, tumor growth, and metastasis—such as AGR2, which enhances the metastatic potential of CRC cells." (PMID 41299673, 2025). "This AGR2-driven axis not only promotes tumor survival under stress but also correlates with poor patient outcomes and resistance to standard-of-care therapies." (PMID 41326375, 2025). "The overexpression of AGR2 is known to facilitate tumor cell proliferation, invasion, metastasis, and EMT." (PMID 41239615, 2025). "Multiple studies show that secreted AGR2 contributes to tumor growth and progression, particularly through its role in angiogenesis and as a ligand for cell surface receptors, including C4.4A and LYPD3." (PMID 40867591, 2025). "For the few tumor entities that were previously analyzed for AGR2 expression, our positivity rates were generally in the upper range of earlier data." (PMID 39533806, 2024). "Overexpression of AGR2 is commonly observed in various human adenocarcinomas, where it promotes tumor growth and metastasis, correlating with a poor prognosis." (PMID 38822246, 2024). "AGR2 positivity was found in 103 of 134 tumor categories, and 83 tumor categories contained at least one strongly positive case." (PMID 39533806, 2024). "Similar to ENPP1, AGR2 has been reported to have tumour-promoting activity, including the promotion of proliferation, migration, invasion and therapy resistance." (PMID 39273106, 2024). "Taken together, these data show the ability of novel high-affinity anti-AGR2 antibodies developed in this study to bind and neutralize the pro-tumor activity of soluble AGR2." (PMID 39727484, 2024). "The utilization of monoclonal antibodies targeting AGR2 can effectively enhance tumor cell apoptosis." (PMID 39281319, 2024). "Unraveling the underlying mechanisms is crucial for assessing the potential of therapeutically targeting AGR2 as a strategy to inhibit a pro-metastatic microenvironment and impede tumor metastasis." (PMID 38822246, 2024). "This cascade subsequently elevated AGR2 expression in PNETs, thereby promoting tumor growth and metastasis." (PMID 38341509, 2024). "Inhibiting tumor growth can be achieved by targeting the self-dimerization region of AGR2 with monoclonal antibodies to disrupt eAGR2 activity." (PMID 39062458, 2024). "Alternatively, it is possible that reduced AGR2 expression in tumors derived from AGR2‐expressing normal cells just reflects tumor cell dedifferentiation which usually parallels cancer progression." (PMID 39533806, 2024). "We further analyzed AGR2 expression in tumor and normal adjacent tissue from surgical samples acquired at our center." (PMID 39727484, 2024). "In an SW480 tumour xenograft model, knockdown of AGR2 was seen to mediate the resistance to 5-Aza-2′-deoxycytidine." (PMID 38391955, 2024). "At least an occasional weak AGR2 positivity was detected in 103 of 134 tumor types and tumor subtypes and 83 entities included at least one case with strong AGR2 positivity." (PMID 39533806, 2024).
tumor (continued). "Anti-AGR2 antibodies were developed to generate a highly sensitive reagent for the detection of AGR2 as well as to create a therapeutic that neutralizes the pro-tumor function of extracellular AGR2." (PMID 39727484, 2024). "The successful analysis of 12,434 tumors from 134 different tumor categories provides a comprehensive overview on AGR2 expression in cancer." (PMID 39533806, 2024). "A series of in vivo and in vitro experimental studies have demonstrated that AGR2 promotes tumor invasion and metastasis through ERS." (PMID 39062458, 2024). "AGR2 shows promise as a prognostic marker by influencing the tumor microenvironment and immune infiltration, thereby impacting drug resistance and patient outcomes." (PMID 39062458, 2024). "Among the CAF-induced PNET liver metastasis–related genes, AGR2 and cytokeratin 19 (CK19) were particularly analyzed because of their high fold changes and potential association with tumor aggressiveness." (PMID 38341509, 2024). "The TME comprises a diverse immune component, and AGR2 expression can influence the production of various immune cells involved in tumor eradication." (PMID 39062458, 2024). "AGR2 expression can influence drug resistance in tumor cells via the extracellular signal-regulated kinase/serine–threonine kinase (AKT) pathway." (PMID 39062458, 2024). "During tumor progression, some authors have found that AGR2 and FOXA1 are recognized as prognostic markers during tumor progression, with both proteins interacting and mutually promoting each other at low levels." (PMID 39062458, 2024). "In contrast, AGR2 in pancreatic neuroendocrine tumor cells plays a role in promoting tumor growth and metastasis through interaction with cancer-associated fibroblasts." (PMID 39062458, 2024). "This elevation of miR-342-3p led to reduced AGR2 expression, ultimately demonstrating anti-tumor effects." (PMID 39062458, 2024). "To summarize, intracellular and extracellular AGR2 can interact with other proteins through their intrinsic motifs and secretion functions, playing an essential role in tumor cell growth, angiogenesis, inhibition of apoptosis, and tissue metastasis." (PMID 37197416, 2023). "The analysis of healthy tissues, as well as pre‐and post‐treatment tumour samples, unveiled the upregulation of several ER‐related genes in chemotherapy‐treated samples, among which AGR2 was identified." (PMID 37409695, 2023). "Together, the results suggest that JUP/AGR2/LYPD3 signaling plays a role in maintaining tumor cell stemness and enhances the glycolytic phenotype." (PMID 37924160, 2023). "The in-depth understanding of the mechanism of AGR2 is of great significance for the study of the mechanism of tumor occurrence and development, as well as the early diagnosis, treatment and prognosis of AGR2 as a molecular target in clinic." (PMID 37197416, 2023). "The regulatory effect and mechanism of AGR2 on tumor is an important hotspot in the field of tumor research." (PMID 37197416, 2023). "In the present study, we found that AGR2 is significantly correlated with OS, RFS, and various clinical parameters, including AFP, ALT, the predicted risk metastasis signature score, tumor size, and pathological stage." (PMID 36899352, 2023). "Median (P25, P75) of AGR2 H-scores in tumor tissues [270.0 (180.0, 270.0)] was higher than that in adjacent tissues [150.0 (80.0, 240.0)] (P < 0.001)." (PMID 37568077, 2023). "At the same time, AGR2 can also exist in the extracellular space, serum and urine, which opens up other ways for its role in the tumor microenvironment." (PMID 37197416, 2023). "Dr Fessart also discussed the role of AGR2 in chemoresistance demonstrating that Doxorubicin‐resistant tumour cell lines (MCF7‐R) displayed increased expression and secretion of AGR2." (PMID 37409695, 2023).
tumor (continued). "The existence of extracellular AGR2 can transform non tumor organs into tumor organs and enhance their growth by about 10 times, which is independent of its thioredoxin folding and endoplasmic reticulum retention motif." (PMID 37197416, 2023). "UQTs did not express such high levels of those genes but did express certain tumor cell markers such as AGR2, mucin 1 (MUC1), and SERPINB126." (PMID 37771785, 2023). "AGR2 was slightly more highly expressed in HCC tumor tissues than in normal tissues, and the spliced XBP1 (XBP1 s) level was slightly more highly expressed in HCC tissues." (PMID 36899352, 2023). "Stable expression of AGR2 in the NIH3T3 cell line led to cellular transformation and induced tumor formation in nude mice after xenotransplantation of NIH3T3 AGR2+ cells." (PMID 37175601, 2023). "Results suggest that in ESCC, the AGR2 gene is a promising and predictive gene marker for the response to anti-tumor therapy." (PMID 36327302, 2022). "The expression of genes encoding mucins (MUC1, MUC2 and MUC5A) or involved in mucosa protection (TFF1 and TFF3) were positively correlated with AGR2 expression in most tumour types." (PMID 35857928, 2022). "AGR2 is an oncogene and involved in cell proliferation, invasion and tumour progression via microRNA, circRNAs and several pathways." (PMID 35962061, 2022). "Recently, AGR2 was described to promote tumor metastasis via activation of the mTOR/AKT signaling pathway." (PMID 35962061, 2022). "In recent years, the role of AGR2 in tumor development and progression has become more and more intensively studied." (PMID 36142758, 2022). "Several reports described decreased AGR2 expression in tumor cells exposed to transforming growth factor beta (TGF-β) indicating its potential association with EMT, most probably via the SMAD4 signaling pathway." (PMID 36142758, 2022). "Elevated levels of AGR2 were shown to significantly contribute to aggressive tumor growth, survival, and metastasis development." (PMID 34929376, 2022). "In our preclinical research, we performed detailed analysis of the role of AGR2, currently showing as an important tumor marker." (PMID 36142758, 2022). "In the collections of cell lines of GDSC (Genomics of Drug Sensitivity in Cancer) and CCLE, four tumour cell lines bear a variation in AGR2 coding sequence, among which three are common to the two databases." (PMID 35857928, 2022). "AGR2 is a promoter of cancer cell proliferation, invasion and survival, chemotherapy resistance, metastasis, and tumor growth." (PMID 36358336, 2022). "In the TCGA, we also identified the genes that were co-expressed with AGR2 or AGR3 in five major tumour types (COADREAD, BRCA, LUAD, LUSC and OVCA)." (PMID 35857928, 2022). "Accumulating evidence has shown that AGR2 plays a crucial role in tumor growth, cell proliferation, and cell migration." (PMID 35055132, 2022). "The mean survival until progression was reduced from 38.71 months in patients with AGR2 low-expressing tumours to 12.38 months in patients AGR2 high-expressing tumours." (PMID 34452625, 2021). "Humanized 18A4 (18A4Hu) and murine 18A4 antibodies specifically bind to AGR2 and exhibit some tumor growth inhibition activity." (PMID 34925322, 2021). "Because AGR2 has a strong link with carcinogenesis and tumor dissemination, it has been widely recognized as a proto-oncogene." (PMID 33413231, 2021). "We first conducted immunohistochemistry (IHC) analysis to verify AGR2 protein expression in canine MMT tissues using tumor tissue slides of 34 MMT dogs." (PMID 34679944, 2021). "Results revealed that AGR2 protein levels were significantly elevated in tumor tissues compared with paired normal mammary gland tissues collected from the same patient, in consistence with the IHC data." (PMID 34679944, 2021).